IGF1 (insulin like growth factor 1)
Diseases named in the same sentence as IGF1 in open-access papers (continued):
Sharing a sentence is not in itself a finding about the gene and the disease.
melanoma (continued). "A recent study has demonstrated a protective effect of GCNT2/I-branched glycans in melanomas, with experiments in vitro and in vivo demonstrating that GCNT2/I-branched glycans promoted melanoma growth and survival through IGF-1 and ECM-mediated signaling pathways." (PMID 40034691, 2025). "They prepared HA NPs containing either IGF-1 to target IGF1R expressing melanomas or HA NPs not containing IGF-1." (PMID 35890401, 2022). "Activated fibroblasts affect the acquisition of drug resistance in melanoma in various ways, a.o., through the secretion of growth factors, including HGF, insulin-like growth factor 1 (IGF1), and basic fibroblast growth factor (bFGF), which support cancer cell growth and proliferation." (PMID 33430277, 2021). "The expression of IGF1 mediated upregulation of FGFR3 and STAT3 in both TAB and melanoma cells." (PMID 34830951, 2021). "Interestingly, the deactivation of FGFR3 was also able to overcome the resistance indicting the correlation between IGF1 and FGFR3 in the chemoresistance in human melanoma cells." (PMID 34830951, 2021). "The syngeneic mouse melanoma models are unique as the bGH mice present supraphysiological GH and IGF-1 levels; while the GHRKO mice present supraphysiological GH but highly suppressed IGF-1 levels." (PMID 33291663, 2020). "However, in relevance to our observations of melanoma tumor growth in the mouse models of high-GH-high-IGF-1 (bGH mice) and high-GH-low-IGF-1 (GHRKO mice), we further analyzed melanoma patient data from the human TCGA database using the GEPIA platform." (PMID 33291663, 2020). "Nevertheless, as the GEM cohort included multiple melanoma patients that might provide unique genetic information, the IGF1R SNP rs2229765 and IGF1 SNP rs1520220 were further analyzed in regression models." (PMID 32150843, 2020). "Melanoma secretes fibroblast growth factor 2 (FGF2), which actives B cells through its binding to fibroblast growth factor receptor 3 (FGFR-3) and promotes the release of insulin-like growth factor 1 (IGF-1)." (PMID 33036192, 2020). "The melanoma associations of IGF1R rs2229765 and IGF1 rs1520220 were not replicable in the GENEVA dataset." (PMID 32150843, 2020). "Furthermore, we would like to know how Polyphyllin I regulated melanoma cells apoptosis and autophagy, PI3K/Akt/mTOR signaling pathway activator IGF-1 was used." (PMID 32733943, 2020). "Regarding melanoma cells, it has been demonstrated that they produce basic fibroblast growth factor (FGF2) which triggers the production of the tumor-supportive insulin-like growth factor 1 (IGF-1) by B cells present in the tumor niche." (PMID 31086070, 2019). "In this study, we incorporated Tris DBA-Pd into hyaluronic acid containing nanoparticles, either containing IGF-1 to target IGF1R expressing melanomas, or hyaluronic acid particles not containing IGF-1." (PMID 30824801, 2019). "In this study normal melanocytes, SKMEL28 melanoma cells and nevo-melanocytes isolated from three L/GCMN patients were exposed to niche factors bFGF and IGF1 in vitro at physiological doses, and expression of a panel of pluripotency markers was determined by RT-PCR." (PMID 30675361, 2019). "This was enhanced in the absence of serum, whereas re-addition of only IGF-1 almost completely compensated in protecting melanoma cells against MEK1/2 inhibition by U0126." (PMID 29137261, 2017). "In addition, expression levels of IGF1 and MS4A1 were correlated in stage IV (r = 0.5928 (p = 0.0199), Spearman’s rank correlation) melanomas." (PMID 28928360, 2017). "Pretreatment with BRAFi did not change the ability of 2 of 3 tested melanoma cell lines to induce IGF-1 expression in NB cells; one cell line lost this ability presumably due to modulation of FGF-2 activity." (PMID 28928360, 2017). "Induction of the subpopulations was seen in most melanoma cells tested and was blocked by antibodies to IGF-1 but not by a control isotype antibody." (PMID 28928360, 2017).
melanoma (continued). "We speculate that similar regulation of IGF-1 on RUNX2 expression and activity could exist in melanoma cells, through the activation of IGF-1R and subsequent stimulation of the PI3K and/or the MAPK pathways resulting in RUNX2 positive regulation." (PMID 27102439, 2016). "Stimulation with IGF-1 for 24 h significantly increased the expression levels of STAT3-targeted genes, including survivin, BCL-XL, and MCL-1, while IT pretreatment for 2 h markedly decreased IGF-1-induced survivin, BCL-XL, and MCL-1 expression in human melanoma A375S and A2058 cells." (PMID 27323414, 2016). "We evaluated the impact of IGF-1 on melanoma, by first transfecting B16-F10 cells with an episomal IGF-1 antisense vector and selecting hygromycin-resistant clones (A6, C10, E11 and F9), in which we evaluated intracellular IGF-1 expression." (PMID 27764776, 2016). "IT pretreatment for 6 h did not reduce the levels of phosphorylatedIGF-1R in the IGF-1-stimulated melanoma cells, while IT pretreatment for 24 h significantly decreased the phosphorylated IGF-1R in the IGF-1-stimulated melanoma cells." (PMID 27323414, 2016). "Furthermore, we report that IGF1 can induce the phenotypic and functional effects of epithelial-to-mesenchymal transition (EMT) in melanoma cells." (PMID 25940796, 2015). "As PAPPA is a known modulator of IGF bioavailability, we tested whether bioactive, non IGFBP-bound IGF1 could restore the migratory ability of melanoma cells after silencing PAPPA gene expression." (PMID 25940796, 2015). "Exogenous CDK2, osteopontin, or IGF1 each alone partly relieved the block of proliferation imposed by BRG1 depletion, implicating that more factors, besides the MITF target genes, are involved in melanoma cell survival." (PMID 23349796, 2013). "In the tumors we analyzed, Igf1 was exclusively expressed in WT myeloid cells, but not in KO myeloid cells, while its receptor, Igf1r, was highly expressed in WT melanoma cells compared to KO melanoma cells." (PMID 41429766, 2025). "Interestingly, a study using a xenografted mice melanoma model has reported a vascular remodeling process which is mediated by the transduction signaling of the IGF1/IGF1R axis, contributing to the development of the melanoma cells which have acquired resistance to BRAF inhibition." (PMID 37174072, 2023). "Considering the fact that single-agent therapies often do not produce durable responses in melanoma, future therapeutic strategies blocking the IGF-1/IGF-1R axis may need to consider combination therapies." (PMID 36551732, 2022). "Conversely, small-molecule inhibitors of IGF1R triggered adherens junction formation between A375 cells even in the presence of serum, demonstrating that the absence of IGF1 signaling is both necessary and sufficient to elicit the behavioral changes observed in melanoma cells." (PMID 36229674, 2022). "Furthermore, it was reported that IGF1R expression correlates with melanoma progression, although early observation indicates the absence of IGF-1 expression in melanoma cells." (PMID 33918490, 2021). "However, the study did not include a comparison of the relative expression of the IGF1 isoforms in melanoma cells vs. control and between different cell lines." (PMID 32977489, 2020). "Since estrogen is able to initiate the IGF1 signaling pathway by inducing the expression of IGF1R and its downstream signaling that leads to cell proliferation, the IGF1 and IGF1R SNPs might still provide crucial information on the ER/IGF1R network in melanoma." (PMID 32150843, 2020). "Of the thirteen selected SNPs examined, IGF1 rs1520220 and IGF1R rs2229765 SNPs might appear to be significantly associated with melanoma risk in men but not in women." (PMID 32150843, 2020). "Moreover, we found that GCNT2/I-branched glycans decreased IGF-1 and RGD ligand binding activity on melanoma cells, suggesting that GCNT2/I-branches may modulate IGF1R and fibronectin: integrin signaling through modulation of ligand binding capacity." (PMID 30135430, 2018).
melanoma (continued). "However, the role of endocrine or paracrine IGF1, insulin or IGF2 in an entire organism might reveal additional effects and provide for a holistic analysis of this aspect of IGF regulation in melanoma." (PMID 28223541, 2017). "Interestingly, among the strongly repressed genes (67 genes, downregulated >8-fold, P<0.005) are insulin-like growth factor 1 (IGF1) and osteopontin (OPN, also named SPP1), two factors known to have anti-apoptotic, proliferative, and pro-invasive activity in melanoma." (PMID 23349796, 2013). "Importantly, we find here that several additional pro-survival proteins (osteopontin, IGF1, TGFß2, and survivin) are downregulated after the acute depletion of BRG1, together implicating SWI/SNF as a transcription coactivator important for survival and proliferation of melanoma cells." (PMID 23349796, 2013). "The same relationship held for the ratio IGF-1/IGFBP-3, while the IGF-1 levels per se did not correlate with melanoma stage, suggesting that the apparently protective function of IGFBP-3 is not limited to preventing IGF-1 from stimulating cell proliferation." (PMID 24905466, 2014). "The expression of OPN, IGF1, TGFß2, and survivin was not reported previously to be MITF-dependent in melanomas." (PMID 23349796, 2013). "Although melanoma cells do not produce IGF-1, activation of the MAPK and PI3K signaling pathway by paracrine stimulation of IGF-1 from stromal fibroblasts enhanced survival, migration, and growth of melanoma cells only from biologically early tumors." (PMID 35370981, 2022). "IGF1 on the other hand induced MITF in NBMEL and nevomelanocytes but not in melanoma cells." (PMID 30675361, 2019). "The melanocytes that overexpress bFGF can, without the presence of insulin-like growth factor (IGF-1) and melanocyte-stimulating hormone (MSH), grow and proliferate, and the bFGF secreted by melanoma cells can stimulate proliferation of stromal cells in a paracrine manner." (PMID 27999823, 2016). "Although we demonstrated induction of a mesenchymal phenotype by IGF1 and enrichment of PAPPA in mesenchymal-like melanoma cells, we did not exhaustively study the role of PAPPA in modulating alternative signalling pathways such as TGF-β, another potent inducer of EMT." (PMID 25940796, 2015). "These experiments demonstrate that DNA methylation of the non-CG island P2 promoter of IGF1 can directly silence gene expression, as previously shown when plasmid constructs containing the non-CG island promoters of LAMB3 and RUNX3 genes were transfected into HaCaT cells and 623 melanoma cells." (PMID 25789079, 2015).
ovarian carcinoma (113 papers, 1996 to 2026). A malignant neoplasm originating from the surface ovarian epithelium. "An extensive outcome-wide analysis of cancer risk from the UK Biobank has established an inverse association between IGF-1 and the risk of ovarian cancer." (PMID 38396692, 2024). "In vitro studies of ovarian cancer cells found that exposure to isoflurane increased angiogenesis, cell proliferation, and migration associated with increased levels of insulin-like growth factor 1 and VEGF34." (PMID 36810898, 2023). "In contrast, a pooled analysis of 1270 ovarian cancer cases and 2907 matched controls showed lower IGF‐1 concentrations were associated with higher risk of epithelial invasive ovarian cancer." (PMID 37269192, 2023). "Further research on the association between IGF‐1 post diagnosis and mortality in ovarian cancer patients is needed." (PMID 37269192, 2023). "Here, we focused on the effect of WISP1, IGF1, αvβ3, and Wnt on ovarian cancer and the underlying mechanisms." (PMID 35964060, 2022). "In this MR study of genetically predicted IGF‐1 levels and risk of prostate and ovarian cancer, results were in the same direction as those from observational studies but were not statistically significant." (PMID 32717139, 2020). "IGF1/mTOR and Fas pathways, were also shown to be negatively enriched in platinum sensitive ovarian cancer patients with low risk score." (PMID 29910195, 2018). "Although there is no experimental evidence for the positive association between insulin and ovarian cancer, some studies have shown that the increased serum levels of IGF-1, IGF-1R, and IGFBP-2 were associated positively in patients with ovarian cancer." (PMID 25866823, 2015). "High levels of IGF-1 are also found to be associated with increased disease risk, tumor metastasis and a poor prognosis in ovarian cancer." (PMID 26360832, 2015). "For instance, patients with high circulating levels of IGF1 have an increased risk of developing ovarian cancer before the age of 55, and high levels of IGF1 mRNA and protein are further linked to disease progression." (PMID 25115504, 2014). "Higher levels of IGF1 are also found to be associated with increased disease risk, tumour metastasis and poor prognosis in ovarian cancer via the activation of IGF1-R." (PMID 24237932, 2013). "Measuring serum levels of IGFBP-3 and IGF1 of healthy women proved useful in predicting a woman's risk of ovarian cancer." (PMID 15471544, 2004). "In addition, the TAM-derived IGF1 is directly implicated in the growth and migration of ovarian cancer cells." (PMID 38420122, 2024). "IGF-1, a powerful growth factor, exerts strong effects on each of the key stages of cancer development and higher levels of IGF-1 have been found to be associated with an increased disease risk, tumor metastasis and a poor prognosis in ovarian cancer via the activation of IGF1-R." (PMID 29844867, 2018). "Multiple mechanisms have been proposed through which physical activity may be implicated in the pathogenesis of ovarian cancer including inhibition of ovulation, alterations in circulating sex hormones and insulin-like growth factor 1 (IGF-1), and changes in BMI." (PMID 38019076, 2023). "Increased IGF-1 bioactivity inhibits apoptosis, stimulates cell proliferation and sex steroid synthesis and inhibits sex-hormone binding globulin synthesis, all of which could be implicated in the development of endometrial and ovarian cancer." (PMID 18665189, 2008). "In epithelial ovarian cancer (EOC), tumor-associated macrophages promote angiogenesis via IGF-I secretion in response to angiopoietin-2 (Ang2), highlighting IGF1 as a potential therapeutic target." (PMID 41463024, 2025). "Collectively, these results provide compelling evidence for the critical role of IGF1 signaling in ovarian cancer progression and establish a robust experimental basis for therapeutic targeting of this pathway." (PMID 41463024, 2025).
ovarian carcinoma (continued). "While previous research has focused on IGF1 in cancers like gastric and ovarian cancer, its role in NPC is becoming increasingly recognized." (PMID 41333209, 2025). "This is the first study to suggest a role of PAPP-A2 in ovarian cancer and to demonstrate a prognostic value of IGF-1 and -2 in ascites." (PMID 38396692, 2024). "In this prospective, longitudinal study of 107 women with ovarian cancer and ascites accumulation, we determined corresponding serum and ascites levels of IGF-1, IGF-2, PAPP-A, PAPP-A2, STC1, and STC2 and assessed their relationship with mortality." (PMID 38396692, 2024). "Ovarian cancer patients with high ascites levels of IGF-1 or IGF-2 showed a poorer prognosis reflected in shorter overall survival." (PMID 38396692, 2024). "BRCA1, the well-established susceptibility gene for BCa and ovarian cancer, increases intratumoral IGF-1 protein expression in BRCA mutation carriers suggesting an involvement of the IGF-1/IGF1R axis in BCa pathogenesis." (PMID 36729355, 2023). "On the other hand, overexpression of PON2 in an ovarian cancer cell line decreased cellular proliferation via the inhibition of IGF-1 expression and signaling." (PMID 37337025, 2023). "In this study, elevated PON2 expression blunted ovarian cancer cell proliferation and xenograft tumor growth in mice through inhibiting insulin-like growth factor-1 (IGF-1) expression and signaling transduction." (PMID 37337025, 2023). "Elevated IGF1 induced malignant properties of ovarian cancer cells through activation of PI3K-Akt and Wnt signaling pathway." (PMID 35964060, 2022). "Data obtained in our study demonstrated that WISP1 exerted facilitated properties on ovarian cancer via enhancement of interaction between IGF1 and αvβ3." (PMID 35964060, 2022). "Due to the limited research, the roles of WISP1, IGF1, αvβ3, and Wnt as well as their interaction in the progression of ovarian cancer should be more clearly investigated." (PMID 35964060, 2022). "In vivo experiments also confirmed that upregulated WISP1/IGF1 induced tumorigenesis and metastasis of ovarian cancer cells." (PMID 35964060, 2022). "As previously reported, IGF1 acts as an inducer for human ovarian cancer by activating the PI3K/AKT/mTOR signaling, which is in line with our finding." (PMID 35964060, 2022). "Through GEPIA and UALCAN databases, we found that IGF1 was elevated in ovarian cancer tissues, and the higher the IGF1 expression corresponded to lower survival rate of patients with ovarian cancer." (PMID 35964060, 2022). "As evidence indicated, TGF-β, PI3K-AKT, and Wnt signaling pathways can mediate EMT, while the regulatory mechanism of IGF1 in ovarian cancer is still unclear." (PMID 35964060, 2022). "Pearson’s correlation analysis exhibited that WISP1 expression was positively correlated with IGF1 expression in ovarian cancer tissues." (PMID 35964060, 2022). "The genes positively related to IGF1 expression in ovarian cancer were analyzed by UALCAN database, revealing 389 genes, which were further intersected with 146 tumor metastasis-related genes recommended by UALCAN database." (PMID 35964060, 2022). "Three shRNA sequences targeting WISP1 were constructed and transduced into CAOV4 cells to unravel the action of WISP1 and IGF1 in ovarian cancer." (PMID 35964060, 2022). "For determining the clinical significance of IGF1, the 57 cases of ovarian cancer tissues and adjacent normal tissues were analyzed." (PMID 35964060, 2022). "CAOV4 cells were then injected into nude mice via tail vein to investigate the effect of the WISP1/IGF1 axis on the in vivo metastasis of ovarian cancer cells." (PMID 35964060, 2022). "In conclusion, WISP1 can facilitate ovarian cancer by activating Wnt via the interaction between IGF1 and αvβ3." (PMID 35964060, 2022). "One experiment studied the effects of isoflurane on the expression of tumorigenic markers, such as insulin-like growth factor (IGF-1) in ovarian cancer cells." (PMID 33430347, 2021).